EZH2 (enhancer of zeste 2 polycomb repressive complex 2 subunit)
Diseases named in the same sentence as EZH2 in open-access papers (continued):
Sharing a sentence is not in itself a finding about the gene and the disease.
tumor (continued). "Tumor tissues from ICB nonresponders exhibited higher levels of both tumoral USP22 and EZH2 expression and lower tumoral β2M expression when compared with biopsies from patients who were ICB responsive." (PMID 41252204, 2025). "In contrast, SUZ12 did not co-localize with EZH2 or EED, suggesting a possible disruption of PRC2 complex formation or altered subcellular dynamics in the tumor context." (PMID 40766612, 2025). "Interestingly, EZH2 expression was remarkably higher within the area of intact p16 and 9p21.3, while the Ki-67-index was higher in the area with p16 and 9p21.3 losses, suggesting that these features can be highly heterogeneous and do not necessarily correlate within the same tumor as expected." (PMID 40718644, 2025). "Intriguingly, neither genetic nor pharmacological Usp22 inhibition had any effect on EZH2 mRNA expression in MC38, 4T1, and RM1 tumor cells, suggesting that Usp22 regulates EZH2 at the posttranscriptional level." (PMID 41252204, 2025). "In summary, the lack of FAT1 promotes EZH2 inactivation, affecting the EMT process in tumor cells, coordinating epigenetic changes, and maintaining the epithelial state." (PMID 38600608, 2024). "When comparing tumor and adjacent non-tumor prostate tissues, we found that DNA hypermethylated regions are enriched for PRC2/H3K27me3 pathways and EZH2/SUZ12 cofactors." (PMID 38566104, 2024). "It has been suggested that lack of EZH2 would lead to failed transcriptional silencing of CDK-Inhibitor 2A (p16) in the PDX1- positive metaplastic lesions, accelerating Kras-driven neoplasia." (PMID 40135141, 2024). "Previously, EZH2, SUZ12, EED, MTF2 and JARID2 have all been suggested to not only act as oncogenes, but also to have tumor suppressor activities, depending on the type of cancer." (PMID 38562687, 2024). "Furthermore, EZH2 inhibitors could prevent the negative effects of EZH2 overexpression on NK cells, thereby enhancing NK cell activation and differentiation and restoring their cytolytic activity to enhance anti-tumor immunity." (PMID 38254784, 2024). "It should be emphasized that EZH2 and HDAC inhibitors effectively kill CRPCs in vitro and trigger frank tumor regression in vivo rather than cytostasis, which is typically not observed in castration-resistant models." (PMID 37104245, 2023). "To complement these observations, we also analyzed UBE2L6 expression in five random fields of tumor sections and plotted it against EZH2 expression scores, revealing a negative correlation between UBE2L6 and EZH2 (linear regression R2 = 0.62, p < 0.0001)." (PMID 36906655, 2023). "Based on quantitative PCR (qPCR) of mRNA isolated from tumor and adjacent non-tumor liver tissues of 24 patients with HBV-related HCC, EZH2 expression was significantly overexpressed in most HCC tissues (87.5%)." (PMID 37689710, 2023). "EZH2 levels are significantly higher in MNA cells than in non-MNA cells and this leads to the inactivation of a tumor suppressor program in NB." (PMID 38069407, 2023). "Enhancer of zeste homolog 2 (EZH2), an enzymatic subunit of PRC2 complex, plays an important role in tumor development and progression through its catalytic and noncatalytic activities." (PMID 36642705, 2023). "In conclusion, in addition to the partial non-canonical function of EZH2, PRC2 mainly exerts oncogenic or tumor-suppressive effects through its gene silencing function, depending on the cancer type." (PMID 36076977, 2022). "Notably, M2-like tumour-associated macrophages (TAMs), including CD206- and PD-L1-positive macrophages and microglia, infiltrated the tumour mass in each group at marked frequencies in the tumour mass (day 28), regardless of EZH2-92aa KD or the administration of NK cell therapy." (PMID 35970825, 2022). "Small molecules targeting EZH2, EED/EZH2 or EED/H3K27me3, although effective do not achieve complete tumor regression." (PMID 36105358, 2022).
tumor (continued). "EZH2, HMGB3 and UCK2 expressed higher in tumor compared with normal tissues, while NOTCH2 and ODF2 expressed lower in tumor compared with normal tissues." (PMID 32699528, 2020). "Invitro and animal experiments were not conducted to confirm the role of EZH2 in the growth and progression of HCC, and its relationship with the infiltration of immune cells into the tumor microenvironment." (PMID 33180829, 2020). "Sorted cells expressed MELK, EZH2, and NF-κB in nuclei, however little signal was detected in the CD133− group representing non-GSC tumor cells (p < 0.01 and p < 0.001)." (PMID 31380279, 2019). "Although several compounds of EZH2-SET inhibitors have entered into clinical trials, some have already failed in phase I at least partly due to the negative mediation of anti-tumor immunity." (PMID 31752930, 2019). "Additionally, EZH2 has been shown to also possess non-enzymatic functions, leading to a situation that raises the possibility that the enzymatic inhibitors currently employed in clinical trials may not fully suppress EZH2 activity as well as its tumor promotion." (PMID 30510924, 2018). "Animal studies have shown intratumoral knockdown of EZH2 promotes tumour regression, this observation being confirmed in HCC cell lines which lose their tumour initiating properties in the absence of EZH2." (PMID 29079534, 2017). "Overexpression of Ezh2S21A induced 2-fold and 4-fold more CD62Lhi CD8+ T cells in the spleen and tumor, respectively, than GFP- and Ezh2-Pmel-1 cell recipients, but did not prevent Pmel-1 cells from differentiating into CD62Llo TEFF in vivo." (PMID 29242551, 2017). "Consistently with these findings in patients, indicating a tumor-suppressive role of EZH2 in MDS, mice lacking Ezh2 have enhanced initiation and progression of Runx1-mutant MDS." (PMID 27793053, 2016). "Our present studies extend these findings and show that Ezh2 and Bmi-1 levels are substantially enriched in SCC tumor forming stem cells as compared to non-stem cells." (PMID 24376802, 2013). "In contrast, there was no apparent effect of reduced EZH2 levels, either by Ezh2 knock-down or DZNep treatment, in BRCA1-proficient tumor cells." (PMID 19709408, 2009). "Notably, in the absence of TTP, combined inhibition of EZH2 and PI3K/mTOR signaling failed to elicit anti-tumor effects in both DKO and PPKO tumor cells, particularly under castrate conditions." (PMID 40832297, 2025). "Conversely, further analysis of surviving tumor cells 48 hours after cocultivation with OT-I CD8+ T cells showed a higher USP22 and EZH2, but not EZH1 and USP27 expression, implying that the increased USP22 and EZH2 expression is involved in tumor immune evasion." (PMID 41252204, 2025). "Interestingly, USP22 appears to selectively control EZH2 but not any other PCR2 complex proteins including EZH1, SUZ12, and EED in tumor cells." (PMID 41252204, 2025). "Additionally, administration of DYB‐03 did not have a significant inhibitory effect on tumor growth in A549 double knockdown cells, indicating that DYB‐03 exerts antitumor activity by targeting HIF‐1α and EZH2." (PMID 38072662, 2024). "Additionally, its interaction with EZH2 introduces a novel regulatory mechanism not previously explored in KIRC, highlighting its distinct role in tumor progression and potential as a therapeutic target." (PMID 39742277, 2024). "Both the canonical (EZH2-PRC2) and noncanonical (EZH2-TAD-Myc-coactivators) functions of EZH2 contribute to oncogenesis, elucidating the limited and gradual efficacy of inhibitors targeting EZH2’s catalytic function in anti-tumor effects." (PMID 38534385, 2024). "For example, in a tumor cell without the expression of ARID1A, the elevated methyl transferase activity of EZH2 will suppress the function of Th1-type chemokines and IFN-g-responsive genes by converting H3K27 to H3K27me3 on the Th1-type chemokines and the IFN response promoters." (PMID 37371564, 2023).
tumor (continued). "Additionally, we report a progressive increase in EZH2/PRC2 activity in PTC, as evidenced by increased EZH2 and SUZ12 expression in tumor tissue compared to adjacent nontumoral tissue in the TCGA database." (PMID 37175580, 2023). "Consistently, the tumor sizes in the zebrafish HCC primary tumors (KRASG12V+) decreased with Roblitinib treatment, while in the zebrafish HCC primary tumors containing ectopic EZH2 expression, Roblitinib failed to inhibit the HCC cell growth." (PMID 37085881, 2023). "However, no significant reduction in EZH2-positive cells was observed in TMZ-treated PBT24 and SF8628 tumor tissue compared to their controls in our study." (PMID 35216113, 2022). "Interestingly, we did not register a complete deletion of the Ezh2 exon 14–15 using the RCAS-CRE system as detected by qualitative PCR, either in formalin-fixed paraffin embedded (FFPE) tumor tissues or in in-vitro cultured P3 neuronal precursors." (PMID 35395831, 2022). "EZH2 gene/protein is frequently upregulated in primary HCC and this correlates to poor prognosis of HCC: Metastatic HCC features, including the presence of venous invasion, direct liver invasion, and the absence of tumor encapsulation." (PMID 32806748, 2020). "Using our previous microarray dataset, we determined that the expression of EZH2, RRM1 and FOXM1 was significantly increased in tumor compared with the non-tumor lung tissue and the expression of BTG2, NFIB and SELENBP1 was significantly decreased in the tumor compared to non-tumor." (PMID 30458017, 2018). "It is reported that curcumin, a natural component of turmeric, can reduce EZH2 expression through the MAPK pathway rather than by increasing protein degradation, which could inhibit tumor cell proliferation." (PMID 28415635, 2017). "It is very likely that these chemokine genes play a tumor suppressor role in cancer, and their consistent negative correlation with expression of epigenetic enzymes such as DNMT1 or EZH2, suggest that their underexpression may be under epigenetic control." (PMID 27899617, 2017). "Overall, these data also suggest that targeting EZH2 in these tumors, without targeting KDM2B may not be sufficient to inhibit tumor growth." (PMID 28515962, 2017). "On the other hand, negative correlation of EZH2 (r = -0.53, p < 0.001), SALL4 (r = -0.4, p < 0.001), TCF3 (r = -0.45, p < 0.001) with Hp in high tumor Hp expression group could also be an indication of relative well cancer differentiation." (PMID 28158312, 2017). "Interestingly, there was no significant changes between tumor and normal tissue in enzymes writing or erasing H3K4 marks including Kmt2a, Ash1l, Cxxc1, Kdm1a and Ezh2." (PMID 25823816, 2015). "Moreover, we found that the expressions of Ezh2 and plexin-B1 were not negatively correlated with miR-214 in miR-214-downregulated HCC tumor samples (data not shown)." (PMID 22359598, 2012). "Apart from EZH2, the following clinical and histopathological features showed a statistically significant impact on CSS in non-metastasized RCC patients in univariate analyses: tumor stage, grading, Karnofsky performance status, and histopathological subtype." (PMID 20920340, 2010). "Interestingly, our results demonstrated that tunicamycin (TM), a well‐established ER stress inducer, failed to promote ERAD for both EZH2 and MYC, implying that substrate specificity for ERAD may be dependent on stress conditions as well as tumor type." (PMID 39823459, 2025). "The tumor was diagnosed as b-HCA by standard immunostaining assays, which also showed expression of AR (androgen receptor) in the lesional cells, indicating receptor activation, but with no increase in EZH2 (Enhancer of Zeste 2 Polycomb Repressive Complex 2 Subunit) protein expression." (PMID 39061609, 2024).
tumor (continued). "Notably, they showed that tumor burden was more significantly reduced when mice were treated with MS177 instead of with UNC6852, a PROTAC that selectively targets EED and therefore the PRC2 activity but not the PRC2-independent activity of EZH2." (PMID 36105358, 2022). "Not coincidentally, EZH2 inhibitors were also able to promote STING pathway-mediated T-cell infiltration and antitumor effects, suggesting that these two inhibitors may play synergistic roles in modulating the tumor immune microenvironment." (PMID 36263120, 2022). "An experimental study found that EZH2 (Enhancer Of Zeste 2 Polycomb Repressive Complex 2 Subunit) inhibitors did not dramatically alter MDSC tumor infiltrate populations, but significantly reprogrammed TAM infiltrates, decreasing tumor-promoting M2 TAMs and increasing tumor-inhibiting M1 TAMs." (PMID 34830209, 2021). "However, no other correlations were observed between EZH2 expression level and other clinicopathological characteristics of patients with LUAD such as age, sex, lymphatic metastasis status, distant metastasis, TNM stage, and tumor recurrence status." (PMID 33276757, 2020). "Previous studies have shown that EZH2 silencing reduced cancer cell growth, migration and invasion in SCCHN, but which lack transgenic animal experiments and does not involve the influence of EZH2 on tumor microenvironment regulation of tumor genesis and development." (PMID 33505420, 2020). "Furthermore, our studies represent that AXL/EZH2/TGF-β1, but not Sox2, might play a pivotal role in tumor invasion, migration and EMT." (PMID 29642503, 2018). "PRC2, which includes EZH2, suppressor of zeste 12 (SUZ12), and embryonic ectoderm development (EED), trimethylates histone 3 lysine residue 27 (H3K27) and leads to silencing of genes involved in processes such as stem cell maintenance and tumor progression without DNA sequence modification." (PMID 27502594, 2016). "In addition to the difference in tumor volume, we also found tumor tissues formed by injection of SGC7901/miR-217 cells displayed much weaker staining of EZH2, Ki-67 and CD31 than those formed by negative control (SGC7901/miR-Ctrl) cells as detected by immunohistochemical analysis." (PMID 25869101, 2015). "The pharmacokinetics of VX-689, MI-2, OTX-015, EZH2 inhibitors, and PTC-596 in the brain remain unknown, while studies on a multi-kinase drug (BMS-754807) demonstrated efficacy against H3.3-K27M murine cells in vitro but failed to reach IC50 levels in tumor tissue when dosed at 50 mg/kg in vivo." (PMID 30340362, 2018).
cancer (2,020 papers, 2004 to 2026). A tumor composed of atypical neoplastic, often pleomorphic cells that invade other tissues. "Classic examples include PARPis in BRCA1/2‐deficient tumours and EZH2 inhibition in ARID1A‐deficient cancers." (PMID 41537447, 2026). "Activating mutations or high‐level EZH2 expression are common in cancer, making EZH2 a promising therapeutic target." (PMID 40181550, 2026). "In conclusion, our findings reveal that NRF1 is a dominant cause of EZH2 overexpression in human cancers and that NRF1 overexpression increases the sensitivity of cancer cells to EZH2is." (PMID 42140904, 2026). "Both overexpression and mutations of EZH2 have been implicated in the progression of various cancers, highlighting its potential as a promising therapeutic target." (PMID 41544165, 2026). "The efficacy of Tazemetostat was also evaluated in BRCA‐1 associated protein 1 (BAP1) inactivated cancers as preclinical data suggest that BAP1 inactivation leads to enhanced EZH2 expression associated with pronounced sensitivity to EZH2 inibition." (PMID 40181550, 2026). "Dysregulation of EZH2 has been associated with the development and progression of many types of cancer." (PMID 41153744, 2025). "More studies have confirmed that a variety of cancers are associated with EZH2 mutations and expression imbalance, and it is an important target for cancer therapy, with 319 targeted drugs currently available." (PMID 39944135, 2025). "EZH2 overexpression is a hallmark of various cancers and is associated with disrupted methylation patterns that promote tumorigenesis." (PMID 40959108, 2025). "EZH2 is highly expressed in several cancer types and has been associated with progression and metastasis in HCC, bladder cancer and breast cancer." (PMID 39850359, 2025). "The advancement of cancer is linked to the overexpression of the enhancer of zeste homolog 2 (EZH2)." (PMID 40227645, 2025). "HOTAIR and EZH2 have been implicated in significant pro-tumorigenic roles across various cancer types, and their expression is closely associated with sensitivity to platinum-based chemotherapy." (PMID 41353219, 2025). "The study revealed that the transcription of EZH2 is ELK1-dependent, and that EZH2’s overexpression is associated with aggressive cancer types like TNBC and EGFR-overexpressing BC." (PMID 40862737, 2025). "Usually, the overexpression of EZH2 is associated with poor prognosis and short survival time in patients with cancer." (PMID 40028035, 2025). "Dysregulation of EZH2 activity has been implicated in various cancers, making it a significant focus of oncological research." (PMID 40562788, 2025). "The R690 mutation in EZH2 is the second most common mutation observed in cancer, and the affected residue is critical to the docking of EZH2 inhibitors targeting the catalytic SET domain of EZH2." (PMID 40562788, 2025). "Inhibition of enhancer of zeste homolog 2 (EZH2) has been shown to improve T-cell-mediated killing and susceptibility to immune checkpoint inhibitors in a variety of cancers." (PMID 41221671, 2025). "Activating GoF cancer-associated hotspot mutations and amplifications in EZH2 have been reported in solid tumours and lymphomas in which histone hypermethylation has been linked to altered gene expression and transformation." (PMID 37828086, 2025). "The UP genes also returned five sets associated with other types of cancer, one describing genes under the regulation of EZH2 (catalytic subunit of PRC2 responsible for H3K27me3) and one describing mammary stem cells." (PMID 40067149, 2025). "Aberrant EZH2 expression has been associated with increased malignancy and poor prognosis in various cancers." (PMID 41209556, 2025). "Previous studies have demonstrated that EZH2, an epigenetic regulator, is significantly upregulated in aggressive cancer subtypes, including TNBC, and is associated with poor prognosis and metastatic potential." (PMID 40038276, 2025).